PLGLB2 (plasminogen like B2)
Description:
May bind noncovalently to lysine binding sites present in the kringle structures of plasminogen. This may interfere with the binding of fibrin or alpha-2-antiplasmin to plasminogen and may result in the localization of activity at sites necessary for extracellular matrix destruction.
Synonyms: PLGP1
Tractability: Antibody: UniProt places it where antibodies can reach, with medium confidence; UniProt predicts a signal peptide or a membrane-spanning region; its Gene Ontology location is reachable by antibodies, with medium confidence.
Gene: Protein-coding gene on chromosome 2 (87,748,085 to 87,759,723, forward strand). Ensembl gene ENSG00000125551.
Subcellular location: Secreted
Subcellular location (Human Protein Atlas): Vesicles; Predicted to be secreted
Gene Ontology:
Cellular component: extracellular region
Homologues: Paralogues in human: PLGLB1 (100% identical), PLG (96% identical), PRSS50 (11% identical), PRSS33 (10% identical), PLAT (9% identical), OVCH1 (8% identical), TMPRSS12 (6% identical), KLK9 (5% identical), PRSS27 (5% identical), GZMM (4% identical), KLK15 (4% identical), PRSS48 (4% identical), and 2 more.
Diseases named in the same sentence as PLGLB2 in open-access papers:
PLGLB2 is named in the same sentence as 1 disease in open-access papers, as found by Europe PMC text mining. Sharing a sentence is not in itself a finding about the gene and the disease.
PLGLB2 shares sentences with these, for which no sentence is quoted: scrub typhus (2 papers).